PRL (prolactin)
Diseases named in the same sentence as PRL in open-access papers (continued):
Sharing a sentence is not in itself a finding about the gene and the disease.
breast cancer (continued). "In this review, we illustrated and summarized the correlations between endocrine therapy resistance in breast cancer and PRL, as well as the pathophysiological mechanisms and clinical practices." (PMID 34651424, 2021). "In conclusion, we have found OXTR overexpression induces ERBB2+ mammary tumors through activation of PRL/p-STAT5 pathway." (PMID 34099636, 2021). "The activation of ERα promotes ligand-independent transcriptional initiation of ERE dependent target genes which seems to be an important factor in the proliferative and transcriptional actions of PRL in breast cancer cells." (PMID 34572912, 2021). "By using a miRNA array in T47D human breast cancer (BC) cells, it was shown that PRL upregulates 21 miRNAs through MAPK/ERK and PI3K/Akt pathways." (PMID 34745013, 2021). "We demonstrate that humanization of PRL in the NSG-Pro mouse model resolves the critical incompatibility between mPRL and hPRLR and restores cooperative ER and PRL signaling in engrafted human breast cancer cells." (PMID 34524841, 2021). "These can occur because the estrous cycle that stimulates prolactin can be different in each individual mouse, which can affect differences in the growth rate of mammary tumors in rat39,40." (PMID 34164110, 2021). "In conclusion, PRL is closely correlated to the tumourigenesis, development and endocrine therapy resistance of breast cancer." (PMID 34651424, 2021). "All these data indicated that PRL is closely correlated to the tumourigenesis and development of breast cancer." (PMID 34651424, 2021). "PRLR is involved in the activation of MAPK/ERK signaling in several breast cancer cell lines, which mediate PRL-induced biological activity in these cells." (PMID 34572912, 2021). "Tumor Tregs were sorted from LFPRLR SMO- or Control SMO-treated mice and then placed in co-culture with fresh 4T1 breast cancer cells in vitro in the presence of prolactin (100 ng/mL) for 48 h." (PMID 34375938, 2021). "The elevation of serum PRL levels had the same incidence in both groups of patients: with benign and malignant breast tumors." (PMID 34945164, 2021). "Contrary to the believed role of PRLR in breast cancer progression, recent studies have indicated that PRL exerts anti-tumorigenic effects in HER2 positive breast cancer cells through regulation of stemness." (PMID 34572912, 2021). "With regards to the prolactin signaling pathway, prolactin functions as a cytokine immune system, especially in breast cancer, which has the strongest correlation with an increased expression level of prolactin and prolactin receptors." (PMID 34641448, 2021). "Shemanko proved that prolactin had an effect on reducing the time to bone metastasis in patients with breast cancer and provoked breast cancer cell-mediated lytic osteoclast formation." (PMID 35096937, 2021). "Breast cancer cells were reported to up-regulate human prolactin receptor (PRLR) to assist their growth through the utilization of prolactin (PRL) as the growth factor, which makes PRLR a potential therapeutic target for breast cancer." (PMID 34077462, 2021). "Both compounds bound to the extracellular domain (ECD) of the PRL receptor (PRLR) at 1–3 micromolar affinity and abrogated PRL-induced breast cancer cell (BCC) invasion and malignant lymphocyte proliferation." (PMID 34071395, 2021). "Exogenous PRL stimulation remarkably reduced the proliferation, colony formation, metastasis, and invasion of breast cancer cells, while miR‐339‐5p expression's suppression reversed these processes in vitro." (PMID 34651424, 2021). "Several lines of mechanistic evidence support a synergistic interaction between PRL and estrogen signaling in human breast cancer." (PMID 34524841, 2021). "While the dichotomous actions of PRL in the normal mammary gland versus breast cancer (e.g., “milk versus malignancy”) are yet to be fully resolved, substantial evidence exists for PRL/hPRLr involvement in tumorigenesis." (PMID 33772010, 2021).
breast cancer (continued). "PRL signaling acts upstream of PR signaling, and thus it can regulate the development of breast cancer by PR." (PMID 34034721, 2021). "The study on PRL and its receptor would help explore reversing endocrine therapy‐resistance for breast cancer." (PMID 34651424, 2021). "S3, D to G), suggesting that the PRL-humanized mouse model can facilitate the dissemination of ER+ cancer cells to diverse sites, as it frequently occurs in patients with ER+ breast cancer." (PMID 34524841, 2021). "With respect to the preservation of fertility options and perhaps, too, to prevent breast cancer, osteoporosis, and post-menopausal venous thrombosis, it would be safest to treat women with prolactin-sparing antipsychotics." (PMID 34575706, 2021). "NRL-PRL transgenic mice which mimic autocrine PRL effects develop aggressive mammary tumors of luminal B subtype." (PMID 34572912, 2021). "Conversely, pS780 is PRL-independent, confirming earlier reports that it is constitutively phosphorylated, and occurs in both luminal breast cancer cell lines and PDX lines, but also in the basal-like breast cancer cell line MDA-MB-43631." (PMID 34188118, 2021). "Several studies using breast cancer cells have shown that PRL activates unliganded ERα through phosphorylation at Ser118 and Ser167 residue." (PMID 34572912, 2021). "The relevance of autocrine PRL in tumor initiation and its role in breast cancer progression has been well studied in transgenic mice models." (PMID 34572912, 2021). "Conversely, estrogen can alter PRL-induced signaling by regulating the transcription of PRL in breast cancer cells and in rat pituitary cells." (PMID 34572912, 2021). "For example, the neutralizing antibody LFA-102 antagonizes PRLR signaling and proliferation in breast cancer cells and regresses PRL-dependent tumor xenografts." (PMID 34107902, 2021). "The hormone prolactin (PRL) and its receptor (hPRLr) are significantly involved in breast cancer pathogenesis." (PMID 33772010, 2021). "The PRLR/PRL (prolactin ligand) signaling axis contributes to estrogen-insensitive breast cancer growth and development." (PMID 34107902, 2021). "Here, phosphorylation of S726-, S780-, and Y694-STAT5a in response to prolactin in MCF7 luminal breast cancer cells was investigated with STAT5a knockdown and rescue with Y694F-, S726A-, or S780A-STAT5a, where the phospho-sites were mutated." (PMID 34188118, 2021). "Although a role for PRL/hPRLr in breast cancer has been well-documented, efforts to tease out the functional and clinical significance of PRL in malignancy have largely been displaced by its role in normal physiology." (PMID 33772010, 2021). "PRL in breast cancer cells via PRLR/JAK2 can also induce phosphorylation of ERBB2/HER2, which in turn activates the downstream RAS/MEK/ERK pathway required for ERα phosphorylation." (PMID 34572912, 2021). "Prolactin-humanized mice promote growth and metastatic progression of estrogen-dependent patient-derived breast cancer." (PMID 34524841, 2021). "Breast carcinoma cell proliferation is blocked through agonists of cannabinoids receptor of breast carcinoma cells via significant affinity nerve growth factor (Trk) and down-regulation of prolactin (PRL) receptors." (PMID 34205169, 2021). "Many lines of evidence demonstrate that both circulating and locally produced PRL increase breast cancer (BC) growth and metastases and confer chemoresistance." (PMID 34071395, 2021). "A study that examined several hundred breast carcinomas found high correlations between tumor PRL expression and metastases, as well as shorter patient survival." (PMID 34071395, 2021). "The role of PRLR in the etiology and proliferation of breast carcinoma induced by prolactin (PRL) has been well established." (PMID 34572912, 2021).
breast cancer (continued). "They investigated actin remodeling after PRL treatment in breast cancer cells, and they found an increase in ruffles and pseudopodia formation and thickness of the perimembrane area, indicating an increased migration activity." (PMID 33233365, 2020). "To investigate the possible molecular mechanisms underlying the reduced STAT5 activation observed upon Rab6a deletion, we took advantage of T47-D, a human breast cancer-derived cell line commonly used for studying PRL-induced signaling events." (PMID 32895290, 2020). "Despite the biological and clinical relevance of the prolactin/PRLR axis, incomplete knowledge of the underlying network has largely precluded its therapeutic exploitation in specific breast cancer subtypes." (PMID 33335078, 2020). "Studies have shown that the occurrence and development of breast cancer are closely related to GH/PRL, and PRLR and GHR are co-expressed on breast cancer." (PMID 33362552, 2020). "Similar to what has been reported for estrogen and progesterone, studies in vitro implicate a role for prolactin in breast cancer cell proliferation and survival, and high levels of this hormone have been shown to drive mammary tumor development in mice." (PMID 33335078, 2020). "Nonetheless, evidence regarding the role of prolactin on breast cancer carcinogenesis remains conflicting." (PMID 32831062, 2020). "Additional circulating effectors of breast cancer spread to bone have been discovered including prolactin (PRL)." (PMID 32751181, 2020). "Observational studies show that patients with higher plasma prolactin levels have increased risks of breast cancer and increased risks of breast cancer progression and mortality." (PMID 32831062, 2020). "Prolactin is closely related to breast cancer, while liver metastases often occur in breast cancer patients." (PMID 33294448, 2020). "Dysregulated PRL/PRLR or GH/GHR activity has been associated with the development of various cancers, including breast cancer." (PMID 33362552, 2020). "Recent studies have, however, questioned the role of prolactin in breast cancer development/progression and have highlighted a putative suppressor role in breast tumorigenesis." (PMID 33335078, 2020). "The prolactin/PRLR-signaling axis has been consistently shown to play a permissive role in the development of primary breast carcinomas and distant metastatic lesions." (PMID 33335078, 2020). "In breast cancer of women, prolactin seems to show different actions, which are partially dependent on the remaining molecular status of the cancer type." (PMID 31581718, 2019). "While the role of PRL in breast cancer has yet to be fully defined, PRL and its signaling pathway Jak2/Stat5 were shown to stabilize cell adhesion complexes and suppress the EMT process and invasive properties of breast cancer cells." (PMID 30987013, 2019). "The panel consisting of prolactin, GH, TSH, eotaxin and E-selectin has shown better accuracy for EC discrimination from ovarian and breast cancers in comparison to prolactin alone." (PMID 31623106, 2019). "L-dopa was recently reported to suppress cellular growth via down-regulation of prolactin-mediated JAK2/STAT5A in breast cancer cells 50, and carbidopa was reported to be an aryl hydrocarbon receptor agonist and to suppress the growth of pancreatic cancer." (PMID 31598163, 2019). "We added a breast cancer PRS using 67 single nucleotide polymorphisms, MD, and circulating testosterone, estrone sulfate, and prolactin levels to existing risk models." (PMID 30180161, 2018). "Breast cancer patients showed significantly reduced prolactin levels and less tumor cells in the S-phase of the cell cycle upon treatment with 1.25–2.5 mg bromocriptine for 5 days." (PMID 30349477, 2018). "Here, we orthotopically transplanted clonal green fluorescent protein (GFP)-labeled PRL-induced ERα + mammary tumor cell lines into syngeneic wild-type (WT) or heterozygous mutant collagen-I female mice (Col1a1tmJae/+, mCol1a1)." (PMID 28103936, 2017).
breast cancer (continued). "In experiments EPL001 inhibits the proliferation in vitro of MCF7 breast cancer cells stimulated by IGF1 and causes a dose-dependent reduction in LH secretion by ovine pituitary cells in vitro and likewise reduces prolactin production." (PMID 29043108, 2017). "In this study we demonstrated the requirement of the participation of PRL/PRLR in transcriptional upregulation/expression of the PRLR induced by E2/ERα in breast cancer cells." (PMID 28423697, 2017). "We previously demonstrated in vitro that a dense/stiff collagen-I matrix shifts the balance of PRL signals from physiological to tumor progressive, and permits PRL and estrogen to reorient collagen-I fibers that mimic aggressive ERα + breast cancers in women." (PMID 28103936, 2017). "Estrogen and PRL synergistically evoke epithelial proliferation in the mammary glands of pigs, whereas overexpression of local PRL in the mammary glands of mice leads to ER-positive mammary tumors, and PRL induces ER expression in cultured breast cancer cells." (PMID 28865492, 2017). "Walpole felt that this action would be of interest in the context of breast cancers which may be associated with high blood prolactin levels, and indeed at Westminster Hospital two patients who had responded well to tamoxifen had tumors which were thought to be prolactin-dependent." (PMID 28955226, 2017). "The involvement of prolactin signaling pathway in breast cancer development is also well documented, and a few works highlight an important cross-talk with the estrogen signaling pathway." (PMID 29657291, 2017). "In previous studies we determined that endogenous PRL which is present in breast cancer cells contributes to basal levels of PRLR expression in MCF-7 and T47D cells and these were magnified by addition of exogenous PRL." (PMID 28423697, 2017). "Epidemiological studies and clinical data have indicated that hormones, including estrogen, progesterone, and prolactin, play important roles in the initiation and progression of breast cancer." (PMID 28251049, 2017). "In other words, blockade/degradation of ERα inhibited the ability of prolactin to elevate the miRNA in both breast cancer and prostate cancer cell lines." (PMID 28422740, 2017). "In order to study the effect of a collagen-dense environment on progression of PRL-induced ERα + mammary cancer, we orthotopically transplanted GFP+ TC2 or TC4 tumor cells into WT or mCol1a1 female mice and monitored growth until end stage." (PMID 28103936, 2017). "Culture of ERα+ breast cancer cells in dense/stiff 3D collagen-I matrices shifts the repertoire of PRL signals, and increases crosstalk between PRL and estrogen to promote proliferation and invasion." (PMID 27344177, 2016). "Increased levels of PRLR in breast cancer indicate their participation in the proliferation of breast tumor and cancer cells induced by prolactin." (PMID 27564112, 2016). "On 2-D tissue culture plastic, PRL is mitogenic for breast cancer cells, and augments estrogen-induced growth." (PMID 27344177, 2016). "Recently, it was shown that prolactin accelerated the breast cancer cell-mediated osteoclast differentiation and bone breakdown by the regulation of breast cancer-secreted proteins." (PMID 27782069, 2016). "Here we further investigate the mechanisms by which pTyr-PAK1 enhances breast cancer cell motility in response to PRL." (PMID 27542844, 2016). "Ser703 of human NHE1 has been widely implicated in regulation of NHE1 activity, and we recently demonstrated its phosphorylation in breast cancer cells in response to prolactin." (PMID 27266704, 2016). "The molecular mechanism, in part, involved the PRL-induced upregulation of SHH at the protein level from breast cancer cells." (PMID 27782069, 2016). "In order to isolate the effect of matrix stiffness on PRL-initiated signals, we cultured breast cancer cells on polyacrylamide hydrogels of increasing stiffness, while holding the collagen concentration constant at 200 μg/ml." (PMID 27344177, 2016).
breast cancer (continued). "Data from human breast cancer cell lines, patient tumor samples and clinical studies indicate that P/PR and PRL/PRLR signaling pathways contribute to early stage human breast cancer progression." (PMID 27248476, 2016). "We have previously demonstrated that PRL promotes breast cancer cell motility in a pTyr-PAK1-dependent manner." (PMID 27542844, 2016). "This unexpected suppressive role of PRL in breast cancer is still emerging and needs to be further elaborated." (PMID 27480353, 2016). "This is the first PRL-based molecular mechanism that has been established in breast cancer metastases, in particular to breast cancer metastases to the bone." (PMID 27782069, 2016). "Prolactin and EGF and their receptors were found to be associated with breast cancer progression and to enhanced MCF7 and T47D cell proliferation." (PMID 27564112, 2016). "The discrepancies in these studies present an apparent conflict in PRL actions in breast cancer: PRL activity has been correlated with aggressive ERα+ tumors, yet activation of the canonical PRL signaling mediator correlates with favorable outcomes." (PMID 27344177, 2016). "For the highest versus lowest levels of plasma prolactin, the pooled RR (95% CI) of breast cancer were 1.16 (1.04, 1.29)." (PMID 27184120, 2016). "The factors secreted by breast cancer cells in the presence of PRL stimulate osteoclast differentiation and lytic activity." (PMID 27782069, 2016). "Here we extend our knowledge on the role for pTyr-PAK1 in PRL-induced breast cancer cell motility and invasion." (PMID 27542844, 2016). "SFKs are a family of oncogenes that contribute to progression of breast cancer, and are important components of PRL signaling cascades." (PMID 27344177, 2016). "In a three-dimensional collagen-I environment, we reported that increased stiffness/collagen density increases PRL signals to the FAK/SFK/ERK1/2 cascade in ERα+ breast cancer cells, while decreasing PRL signals to JAK2/STAT5." (PMID 27344177, 2016). "We discovered that PRL can escalate the osteolytic aspect of the vicious cycle, by stimulating pre-osteoclasts indirectly to differentiate into osteolytic cells through breast cancer secreted factors, such as SHH." (PMID 27782069, 2016). "Moreover, expression/activation of the PRL effector molecule Stat5a was found to associate positively with increased levels of histologic differentiation of breast cancer tissues and to distinguish breast cancer patients with favourable prognosis and response to endocrine therapy." (PMID 27480353, 2016). "Here we provide new insight into the mechanisms regulating PRL-dependent breast cancer cell metastasis." (PMID 27542844, 2016). "Previous literature has demonstrated that prolactin plays an indispensable role in the initiation and development of breast cancer through inducing cell proliferation and inhibiting apoptosis." (PMID 27184120, 2016). "Our findings begin to resolve the apparent dichotomy of PRL actions in breast cancer: PRL can reduce aggressive tumor behavior through STAT5, but increase tumor progression through FAK/SFK/ERK1/2." (PMID 27344177, 2016). "Stiffness similarly modulated PRL signals in another luminal breast cancer cell line, MCF-7 cells, confirming this observation across different cell contexts." (PMID 27344177, 2016). "This is also supported by studies observing elevated levels of circulating prolactin in breast cancer patients, and demonstrating the ability of breast tumors to secrete prolactin." (PMID 25887963, 2015). "Previous study also found that Pak1 regulates prolactin mediated cyclin D1 promoter activity in breast cancer." (PMID 26218748, 2015). "We here show that breast cancer cells exposed to prolactin display an elevated c-Src expression and phosphorylation." (PMID 26733941, 2015). "In dogs as in humans, PRL can be produced not only in the anterior pituitary, but also in normal mammary tissue and malignant mammary tumors." (PMID 26370564, 2015).